LRRC74A (leucine rich repeat containing 74A)
Synonyms: C14orf166B; LRRC74
Tractability: No criterion of Open Targets' tractability assessment is met for any kind of drug.
Gene: Protein-coding gene on chromosome 14 (76,826,372 to 76,870,304, forward strand). Ensembl gene ENSG00000100565.
Genetic constraint (gnomAD): Loss-of-function variants: 22 observed, 32.63 expected, observed/expected ratio (o/e) 0.67, 90% interval 0.48 to 0.96. The upper end of that interval is the gene's LOEUF score, 0.96, which puts it in group 4 of 6, group 1 being the genes least tolerant of losing a copy. Missense variants: 399 observed, 407.22 expected, observed/expected ratio (o/e) 0.98, 90% interval 0.9 to 1.06. Synonymous variants: 139 observed, 164.34 expected, observed/expected ratio (o/e) 0.85, 90% interval 0.74 to 0.97.
Homologues: Orthologues: chimpanzee LRRC74A (99% identical), macaque LRRC74A (93% identical), dog LRRC74A (73% identical), mouse Lrrc74a (72% identical), guinea pig LRRC74A (72% identical), rat Lrrc74a (71% identical), pig LRRC74A (69% identical), rabbit LRRC74A (67% identical), tropical clawed frog lrrc74a (43% identical), zebrafish lrrc74a (43% identical). Paralogues in human: LRRC74B (28% identical).
Diseases named in the same sentence as LRRC74A in open-access papers:
LRRC74A is named in the same sentence as 1 disease in open-access papers, as found by Europe PMC text mining. Sharing a sentence is not in itself a finding about the gene and the disease.
LRRC74A shares sentences with these, for which no sentence is quoted: multiple sclerosis (1 paper).